KCNJ16 (potassium inwardly rectifying channel subfamily J member 16)
Diseases named in the same sentence as KCNJ16 in open-access papers:
KCNJ16 is named in the same sentence as 64 diseases in open-access papers, as found by Europe PMC text mining. Sharing a sentence is not in itself a finding about the gene and the disease. The quoted sentences say what the papers report.
Hypokalemia (10 papers, 2021 to 2024). An abnormally decreased potassium concentration in the blood. "Previous studies have identified several bi‐allelic mutations of KCNJ16 in humans, causing severe hypokalemia, renal salt wasting, and disturbed acid–base homeostasis." (PMID 39414394, 2024). "Patients carrying biallelic loss-of-function mutations in KCNJ16 exhibit disturbed acid–base homeostasis, severe hypokalemia, polyuria, and salt wasting." (PMID 39183338, 2024). "Similarly, defects of KCNJ16 in humans cause hypokalemia, salt wasting, disturbed acid–base homeostasis, and sensorineural deafness." (PMID 39414394, 2024). "Similarly, recent studies revealed that mutations in KCNJ16 (Kir5.1) cause a novel tubulopathy with hypokalemia, salt‐wasting, and disturbed acid‐base homeostasis." (PMID 34665521, 2021). "The importance of the Kir4.1/Kir5.1 channel was further established by the identification of KCNJ10 and KCNJ16 mutations in patients with hypokalemia and hypomagnesemia, mimicking Gitelman syndrome." (PMID 35554666, 2022). "Studies in Kcnj16-knockout mice have also reported a reduction in central chemosensitivity and/or impaired chemoreflexes and other similar phenotypes, including metabolic acidosis, hypokalemia, and low body weight." (PMID 33232300, 2021).
metabolic acidosis (3 papers, 2021 to 2024). "More recently, a novel KCNJ16 variant was identified in a Chinese patient with hypokalemic metabolic acidosis." (PMID 39414394, 2024). "Here, we report the association of biallelic loss-of-function variants in KCNJ16 with a hypokalemic metabolic acidosis phenotype in a 2-year-old female patient, similar to that seen in rodent loss-of-function models." (PMID 33840812, 2021). "Here, we present the first report of an individual with biallelic loss-of-function variants in KCNJ16 presenting with the expected phenotype of hypokalemic metabolic acidosis." (PMID 33840812, 2021).
thyroid cancer (3 papers, 2023 to 2025). "KCNJ16 expression change might come from DNA methylation, cause its expression in thyroid cancer was negatively correlated with DNA promoter methylation and CpG hypermethylation appeared in metastatic group and thyroid papillary carcinoma - tall cell ( > = 50% tall cell features)." (PMID 37208644, 2023). "The inward rectifier potassium channel 5.1 (Kir5.1, encoded by KCNJ16) emerged as an interesting target in thyroid cancer." (PMID 37208644, 2023). "Gene expression quantification of thyroid cancer in TCGA database was extracted and divided into the “high-KCNJ16” and “low-KCNJ16” groups by the median expression." (PMID 37208644, 2023). "Subsequently, we explored KCNJ16 expression in different clinical and pathological features of thyroid cancer." (PMID 37208644, 2023). "Therefore, the role of KCNJ16 and enriched pathways in thyroid cancer need to be further investigated." (PMID 37208644, 2023). "Consequently, Kir5.1, encoded by KCNJ16, emerged as an appealing target in thyroid cancer research." (PMID 38249296, 2023). "Thus, we concluded that KCNJ16 might affect the differentiation and development of thyroid cancer alone or by the Kir4.2/Kir5.1 heterotetramer." (PMID 37208644, 2023). "Considering the coherent correlation between KCNJ16 and TSHR expression and their tendency to decline in tumor tissues, we focused on the potential role of KCNJ16 in thyroid cancer." (PMID 37208644, 2023). "Interesting thing was that KCNJ16 was a favorable prognostic marker in renal cancer and thyroid cancer (data not shown)." (PMID 37208644, 2023).
clear cell renal cell carcinoma (2 papers, 2022 to 2023). "KCNJ16 had the diagnostic, prognostic, and therapeutic value in clear cell renal cell carcinoma." (PMID 37208644, 2023). "Interestingly, KCNJ16 is highly expressed in the renal tubule and collecting duct system, and renal clear cell carcinoma occurs in these sites." (PMID 35721115, 2022).
epilepsy (2 papers, 2021 to 2022). A brain disorder characterized by episodes of abnormally increased neuronal discharge resulting in transient episodes of sensory or motor neurological dysfunction, or psychic dysfunction. "Recently, a rat strain with a homozygous knockout of the Kcnj16 encoding K-channel Kir5.1 gene, leading to the development of AE, was obtained as one more model of channalopathy, leading to epilepsy." (PMID 36428502, 2022). "Mutations in the KCNJ16 gene were previously found in patients with epilepsy." (PMID 36428502, 2022). "Understanding the potential contribution of lesser-studied ion channel genes, such as Kcnj16, to human epilepsy will unlock opportunities to uncover genetic contributors to idiopathic epilepsy and bring forth new treatment strategies for those resistant to current AEDs." (PMID 33232300, 2021). "However, the effect of the loss of function of Kcnj16 on neurological dysfunction and epilepsy has not been evaluated." (PMID 33232300, 2021).
sudden infant death syndrome (2 papers, 2022 to 2023). Unexpected death in infancy which remains unexplained following autopsy, review of the medical history, and investigation of the death circumstances and death scene. "In addition, KCNJ16 has not only been found to be a differentially expressed gene in a variety of cancers, but also KCNJ16 gene mutation is associated with sudden infant death syndrome, Brugada syndrome, lymphoma and other diseases." (PMID 36923292, 2023). "Other studies analyzed the exome data of 155 cases of sudden infant death syndrome (SIDS) and identified the KCNJ16 R137S mutant." (PMID 36923292, 2023).
thyroid tumor (2 papers, 2023). A benign or malignant neoplasm affecting the thyroid gland. "TSHR and KCNJ16 were downregulated in the thyroid tumor tissues, compared with paired normal tissues." (PMID 37208644, 2023). "The author's gene profiling and enrichment analyses revealed that KCNJ16 exhibited downregulation in thyroid tumor tissues compared to normal ones, implicating a pivotal role for KCNJ16 in cell growth and differentiation." (PMID 38249296, 2023).
age-related hearing loss (1 paper, 2021). "In the cochlea, Kir5.1 is expressed in type II, IV, and V fibrocytes in the lateral wall, and Kcnj16 mRNA as well as Kir5.1 protein decrease with age, suggesting that Kir5.1 might play an important role in the pathogenesis of age-related hearing loss." (PMID 33693002, 2021).
Aminoaciduria (1 paper, 2023). An increased concentration of an amino acid in the urine. "Notably, there is no aminoaciduria or glycosuria in either the Kcnj15 or Kcnj16 gene variants, suggesting that Kir4.2 or Kir5.1 dysfunction caused a phenomenon similar to the permanent forms of familial isolated proximal renal tubular acidosis." (PMID 36923292, 2023).
angiosarcoma (1 paper, 2016). A malignant tumor arising from the endothelial cells of the blood vessels. "Notably, expression of several potassium channels is modified in bladder cancer vessels vs controls (KCNC4, KCNG4, KCNS2) and in angiosarcoma vs controls (namely KCNJ16, KCNQ2, KCNJ15, KCNJ12, KCNJ1)." (PMID 27716384, 2016).
Anxiety (1 paper, 2023). Intense feelings of nervousness, tension, or panic often arise in response to interpersonal stresses. "This list contained several ion channels such as Kcnj16 as well as pyrimidine metabolizing and anxiety-related genes." (PMID 37228107, 2023).
Brain tumors (1 paper, 2025). "Brain tumors in REMBRANDT (database) showed altered expression of KCN genes encoding H+-sensitive proteins in glioblastomas versus less invasive oligodendrogliomas of patients on anti-seizure medications, with less KCNJ16/Kir5.1; p = 5.32 × 10−8 in glioblastomas." (PMID 40867621, 2025).
colon cancer (1 paper, 2023). "Furthermore, KCNJ16 is one of the 154 signature genes that could be used to differentiate carcinoma types although no direct association with colon cancer has been reported to date." (PMID 37298272, 2023).
colorectal cancer (1 paper, 2025). A primary or metastatic malignant neoplasm that affects the colon or rectum. "NECAB2, primarily involved in regulating neuronal calcium homeostasis, and KCNJ16, which controls potassium ion flow, have not been previously linked to colorectal cancer development." (PMID 40432804, 2025).
developmental delay (1 paper, 2024). "Here, we identified a novel homozygous variant of KCNJ16, I26T, in an Amish patient affected with polydipsia, developmental delay, and chronic metabolic acidosis with low serum bicarbonate concentration." (PMID 39414394, 2024).
gastric cancer (1 paper, 2015). A primary or metastatic malignant neoplasm involving the stomach. "However, some genes such as HOXC9, FNDC1, STRA6, KCNE2, PGA3 and KCNJ16 haven’t been reported in gastric cancer and their roles remain unknown." (PMID 25928635, 2015).
Generalized hypertrichosis (1 paper, 2024). Generalized excessive, abnormal hairiness. "Interestingly, in the literature there are a series of microdeletions centromeric to KCNJ2/KCNJ16 that have been identified in individuals with congenital generalized hypertrichosis with or without gingival hyperplasia (microdeletion 17q24.2-q24.3 syndrome; MIM 135400)." (PMID 39257002, 2024).
gingival hyperplasia (1 paper, 2024). "In addition, we highlight a previously overlooked potential role for misregulation of the KCNJ2/KCNJ16 genes in the pathomechanism of gingival hyperplasia associated with deletions and other rearrangements of the 17q24.2-q24.3 region (MIM 135400)." (PMID 39257002, 2024). "More broadly, we argue that KCNJ2/KCNJ16 misregulation likely represents the common underlying mechanism in several previously reported patients with gingival hyperplasia and/or hypertrichosis, who harbor deletions and other rearrangements of the 17q24.2-q24.3 region (MIM 135400)." (PMID 39257002, 2024). "As a whole, the deepC prediction supports our hypothesis and suggests that the most probable pathogenic mechanism underlying the severe skeletal malocclusion and gingival hyperplasia involves KCNJ2/KCNJ16 misregulation induced by neo-TAD formation and adopted craniofacial enhancers." (PMID 39257002, 2024). "In line with this, there are at least two instances of complex SV with BPs near the KCNJ2/KCNJ16 genes that potentially modify their regulatory landscape in individuals with syndromic gingival hyperplasia." (PMID 39257002, 2024). "Altogether, a misregulation of the potassium channel KCNJ2/KCNJ16 genes seems likely to contribute to the gingival hyperplasia." (PMID 39257002, 2024).
glioblastoma (1 paper, 2025). The most malignant astrocytic tumor (WHO grade IV). "The OMG difference for KCNJ16, decreased in glioblastomas, became highly significant, p = 5.532 × 10−8, and trends for other genes improved." (PMID 40867621, 2025). "Without using the history of seizure medications, a difference in expression of KCNJ16/Kir5.1 in glioblastomas (less expression), p = 0.05, became significant in glioblastomas using the smaller group of patients on anti-seizure drugs; p = 0.0148." (PMID 40867621, 2025). "Glioblastoma studies included E5 (KCNJ10, KCNN3), E21 (KCNAB2), E26 (KCNE2, KCNJ13), E27 (KCNE4, KCNMB2-AS1), E31 (KCNJ10), E50 (KCND3), and E51 (KCNIP1, KCNJ16, KCNN2)." (PMID 40867621, 2025).
Hirschsprung disease (1 paper, 2014). Hirschsprung disease (HSCR) is a congenital intestinal motility disorder that is characterized by signs of intestinal obstruction due to the presence of an aganglionic segment of variable extent in the terminal part of the colon. "For example, Aebp2, an epigenetic DNA-binding protein involved in Hirschsprung's disease and Waardenburg syndrome, and Kcnj16, a potassium channel involved in respiratory response to hypoxia during breathing, showed VPA-restored expression changes, but the p value was greater than 0.05." (PMID 24968028, 2014).
infertile (1 paper, 2021). "To examine the possible role of Kir5.1 in sperm physiology, we bred mice with a deletion of the Kcnj16 (Kir5.1) gene and observed that 20% of Kir5.1 knock-out male mice were infertile." (PMID 34205849, 2021).
male infertility (1 paper, 2023). The inability of the male to effect fertilization of an ovum after a specified period of unprotected intercourse. "Moreover, the deletion of Kcnj16 in mice, the gene encoding Kir5.1, increases the percentage of sperm with abnormal flagellar morphology and causes subfertility in an age-dependent manner, providing a role for this channel in male infertility." (PMID 37108159, 2023).
ovarian carcinoma (1 paper, 2018). A malignant neoplasm originating from the surface ovarian epithelium. "Examination of the resulting network shows that RPS19, PNOC, SFRP1 and KCNJ16 are connected to other frequently altered genes, including MYC or EIF3E as oncogenes, from TCGA ovarian cancer dataset." (PMID 30255801, 2018).
T-cell lymphoma (1 paper, 2023). "Kcnj16 is frequently mutated in T-cell lymphoma in mice lacking the DNA mismatch repair gene Mlh1, but its function in T-cell lymphoma remains unclear." (PMID 36923292, 2023).
cancer (5 papers, 2022 to 2023). A tumor composed of atypical neoplastic, often pleomorphic cells that invade other tissues. "During exploration, we found the significant role of KCNJ16 in thyroid differentiation and cancer associated signaling pathways." (PMID 37208644, 2023). "Meanwhile, several genomic analyses have shown that KCNJ16 is a DEG in a variety of cancers, such as ATC, PDAC, and HCC." (PMID 36923292, 2023). "We then compared the expression levels of KCNJ16 in cancer and normal tissues in eight GEO databases and found that the expression levels of KNCJ16 were significantly upregulated in normal tissues." (PMID 35721115, 2022). "First, we found that the KCNJ16 expression level was significantly altered in a variety of cancers by pan-cancer analysis, using the SangerBox and was more apparent in ccRCC." (PMID 35721115, 2022). "The detection of DEGs such as KCNJ16 is helpful for the early diagnosis of cancer." (PMID 36923292, 2023). "Consistent with our findings, KCNJ16 has been reported in other cancers." (PMID 37208644, 2023). "In other words, KCNJ16 may be a regulator of thyroid differentiation and cancer migration." (PMID 37208644, 2023). "Thus, KCNJ16 may play a protective role in cell differentiation and cancer progression." (PMID 37208644, 2023). "We identified five genes (KCNJ16, SLC26A4, TG, TPO, and SYT1) as potential cancer treatment targets." (PMID 37208644, 2023). "Although the relevance to HCC is not known, potassium channels, including KCNJ16, are involved in cell cycle, proliferation, cell migration, apoptosis, and angiogenesis in various cancers." (PMID 37610679, 2023). "Taken together, we analyzed the Cancer Genome Atlas (TCGA) database and Gene Expression Omnibus (GEO) database, grouped by TSHR expression level, screened WDTC and ATC, finally identified two differentially expressed genes (DEGs), namely KCNJ16 and SYT1." (PMID 37208644, 2023).
tumor (2 papers, 2022 to 2023). "The mRNA expression level of SYT1 was higher in tumor tissues, while the expression of KCNJ16 was positively correlated with that of TSHR and was decreased in tumor tissues." (PMID 37208644, 2023). "Subsequently, we verified the expression change of TSHR, KCNJ16 and SYT1 in 68 pairs of normal and tumor tissues." (PMID 37208644, 2023). "The expression of TSHR and KCNJ16 was lower in the tumor tissues than that in the paired normal tissues, whereas the expression of SYT1 was upregulated in the tumor tissues." (PMID 37208644, 2023).
kidney disease (1 paper, 2024). "Additionally, we used this system to further unravel potential disease-causing mechanisms and to evaluate the effect of several drug compounds as novel therapeutic options for kidney disease caused by defects in KCNJ16." (PMID 39183338, 2024). "Conjointly, these efforts will contribute to advancing our understanding of KCNJ16 related kidney disease and aid in the development of personalized approaches for diagnosis and treatment." (PMID 39183338, 2024). "Despite kidney fibrosis has, as of yet, not been described as a phenotype for KCNJ16- related kidney disease, we observed an increase in the fibrotic markers collagen-I and fibronectin in our KCNJ16-depleted kidney organoids when compared to the KCNJ16WT control." (PMID 39183338, 2024).
KCNJ16 also shares sentences with these, for which no sentence is quoted: Acidosis (3 papers); Alkalosis (2); Hypertension (2); SeSAME syndrome (2); Andersen-Tawil syndrome (1); asthma (1); atrial fibrillation (1); bladder cancer (1); Brugada syndrome (1); cardiac arrhythmia (1); Channelopathies (1); chronic kidney disease (1); Cooks syndrome (1); cyst (1); deafness (1); Encephalopathy (1); Gitelman syndrome (1); hearing loss (1); hepatocellular carcinoma (1); Hyperkalemia (1); hypertrichosis (1); Hypomagnesemia (1); long QT syndrome (1); lymphoma (1); mental retardation (1); oligodendroglioma (1); parathyroid carcinoma (1); periodic paralysis (1); Polydipsia (1); prostate carcinoma (1).
A further 7 diseases each share a sentence with KCNJ16 in 1 paper.